IL6 (interleukin 6)
Diseases named in the same sentence as IL6 in open-access papers (continued):
Sharing a sentence is not in itself a finding about the gene and the disease.
dengue (continued). "In dengue patients the nine plasma cytokine levels were significantly elevated when compared to healthy controls: GM-CSF, IFN-γ, IL-10, 1L-15, IL-8, MCP-1, IL-6, MIP1β, and TNFα (p = 0.008, 0.0001, 0.0001, 0.0003, 0.0001, 0.001, 0.0003, 0.001 and 0.006 respectively) levels." (PMID 30626045, 2019). "In this study, the multiplex bead array reported for the first time literature in human patients infected with dengue virus revealed that the GM-CSF, IFN-γ, IL-10, IL-15, IL-8, MCP-1, IL-6, MIP-1β, and TNF-α levels were significantly raised in dengue subjects compared to healthy controls." (PMID 30626045, 2019). "The production of IL-6 in PBMC from all symptomatic individuals compared with only a subset of subclinical individuals was a particularly striking finding in this study and suggests its potential role in dengue disease pathogenesis." (PMID 30557313, 2018). "Studies show that elevated levels of IL-6, IL-10, IFN-γ, MIF, and CCL-4 could be used as potential predictors of severe dengue." (PMID 27903271, 2016). "Upon dengue virus infection, PBMC secretes both IL-6 and TNF-α." (PMID 26226614, 2015). "Some have shown that MIF, IL-10, IL-6, MIP-1ß and IFNγ could be used as potential predictors of severe dengue." (PMID 23883139, 2013). "The levels of IL-6 in all dengue cases were higher than healthy controls, but not statistically significant (p>0.05)." (PMID 20090849, 2010). "Many of the studies have also indicated that the levels of pro-inflammatory cytokines are elevated in severe dengue patients, such as interleukin (IL)-6, IL-8, tumor necrosis factor (TNF)-α, and IL-1β, which may result in cytokine storm and increase the severity of dengue in patients." (PMID 36235496, 2022). "Our first priority was to compare the levels of IL-1b, IL-2, IL-4, IL-6, IL-8, IL-10, IL-12p70, IL-17A, IL-33, CD14, CD54, CD62E, CD62L, CD62p, CD106, CD121b, CD154, CD178, GM-CSF, IFN-g, MIF, ST2 and TNF in plasma samples of dengue group, OF group and Healthy group." (PMID 33809042, 2021). "Lack of any difference in IL-6 levels in the general group may be due to variation between groups with differing severity of Dengue." (PMID 30112159, 2018). "Increased levels of TNF-α, IL-1β, IL-4, IL-6, IL-8, IL-13, IL-15, macrophage migration inhibitory factor (MIF), and chemokines CCL2, CCL4, CCL5, and CXCL10 (IP-10) among others, have been reported in patients with dengue hemorrhagic fever (DHF) when compared to dengue fever (DF)." (PMID 29986388, 2018). "Acute serum IL-6, IL-10 and TNF-α levels were measured in 22 dengue patients (12 DF and 10 DHF patients) either on enrollment (n = 19) or 1 day (n = 3) afterwards." (PMID 28393899, 2017). "It was noticed that not all the mice up-regulated IL-6 expression upon dengue virus infection." (PMID 26226614, 2015). "Although the reasons for headache, vomiting and hepatic tenderness in dengue is not clear, it could be due to the high circulating levels of cytokines such as IL-6, TNFα, IL-1β and mast cell products, which are known to be elevated in patients with acute dengue." (PMID 35648794, 2022). "Although, there are some studies showing that IL-6, IL-10 and TNF-α are related to dengue, the roles of IL-37b in dengue fever have not been established." (PMID 37024713, 2023). "Among the host inflammatory biomarkers, GM-CSF, IFN-γ, IL-10, IL-15, IL-8, MCP-1, IL-6, MIP-1β, and TNF-α levels were significantly increased in dengue with and without warning signs, in severe dengue patients in comparison to healthy controls." (PMID 30626045, 2019). "In these studies, IL-1ß, IFN-γ, IL-4, IL-6, IL-13, IL-7, GM-CSF (Granulocyte-macrophage colony-stimulating factor), MIF (macrophage migration inhibitory factor), IL-10 along with several other cytokines have been found to be elevated in patients with DHF when compared to dengue fever (DF)." (PMID 23883139, 2013).
dengue (continued). "Infection also induced neutrophil infiltration in the small intestine, and increased expression of IL-6 and MMP-8 and blockade of TNF-α signaling protected the mice, as demonstrated in a previous severe dengue mouse model using C57/BL6 mice lacking both IFN-α/β and IFN-γ receptors." (PMID 38550855, 2024).
gout (142 papers, 2005 to 2026). A condition characterized by painful swelling of the joints, which is caused by deposition of urate crystals. "IL-6 emerges as a potential risk factor for acute gout attacks, with its involvement in the JAK2-STAT1/3 signaling pathway contributing to the inflammation and pathogenesis process of acute gout through positive feedback mechanisms." (PMID 40170729, 2025). "By investigating the changes in inflammatory mediators such as IL-1β and IL-6 during gout flares, scientists have found a significant association between their increase and joint pain and inflammatory responses in gout patients." (PMID 39980931, 2025). "Previous research has mainly focused on downstream effects, but our study is the first to clinically validate IL-6 as a risk factor for gout." (PMID 40170729, 2025). "Pro-inflammatory mediators associated with gout, such as IL-1 and IL-6, can directly damage inner ear cells." (PMID 40004624, 2025). "Activation of the NLRP3 inflammasome has been implicated in the pathogenesis of gout, leading to the production of inflammatory cytokines such as IL-1β, IL-6, and TNF-α." (PMID 39907694, 2025). "The ointment contains herbal components such as Aconitum carmichaelii and Notopterygium incisum, which inhibit key inflammatory mediators, including TNF-α, IL-1β, and IL-6, thereby reducing acute pain and swelling associated with gout flares." (PMID 39409183, 2024). "Since IL-1β and IL6 have been linked to gout in numerous studies, our main focus was on the connection between CXCL8, CXCL1, and CXCL2 and acute gouty arthritis." (PMID 38686389, 2024). "The formula contains bioactive compounds that inhibit inflammatory cytokines such as TNF-α, IL-1β, and IL-6 and enhance renal excretion of uric acid, providing both symptomatic relief and addressing the underlying causes of gout." (PMID 39409183, 2024). "In order to further investigate the changes in inflammatory factors associated with gout, the expression levels of IL-1β, IL-6, and TNF-α were re-examined in serum." (PMID 37771709, 2023). "Pro-inflammatory cytokines have been implicated in initiation and amplification of the gout flare, such as IL-1β, IL-6, and TNF-α." (PMID 34586567, 2022). "Nucleated uric acid is able to stimulate the production of inflammatory cytokines such as IL-1, TNF-α, and IL-6 in gout, a classic disease caused by hyperuricemia." (PMID 33679237, 2021). "rs114362 in the IL-1B gene, interacting with a CARD8 variant (rs2043211), correlates with increased expression of IL-1β, IL-6, and gout risk." (PMID 33926105, 2021). "Second, studies have shown an association between gout, a chronic inflammatory disease, and high levels of various inflammatory cytokines, chiefly interleukin (IL)-1, IL-6, and IL-8." (PMID 32900384, 2020). "It has been found that the degree of inflammatory activity in GA patients is associated with the IL-6 level, and thus IL-6 is considered to be related to the disease activity of gout." (PMID 32419834, 2020). "Gout is a polygenetic disease, and many studies of candidate genes have identified associations between inflammation-related genes such as IL-1β, IL-6, and IL-8 and susceptibility to gout." (PMID 26890073, 2016). "IL-1β along with other pro-inflammatory cytokines, TNF-α, IL-6, and IL-8 promote neutrophil influx, the primary pathological hallmark of gout." (PMID 26709520, 2015). "Moreover, logistic regression analysis identified IL-6 as a significant risk factor for acute gout attacks." (PMID 40170729, 2025). "This study employs clinical analysis and establishes both in vitro and in vivo models of acute gouty arthritis (AGA) to investigate the role and impact of upstream IL-6 regulation of the JAK2-STAT1/3 signaling pathway on gout inflammation, while exploring potential underlying mechanisms." (PMID 40170729, 2025).
gout (continued). "Colchicine, an anti-inflammatory drug traditionally used to treat gout and pericarditis, has shown efficacy in reducing cardiovascular risk by inhibiting microtubule polymerization and suppressing cytokine release, including IL-1β and IL-6." (PMID 40072051, 2025). "IL-6 is also associated with uric acid-induced inflammation in Gout." (PMID 39202588, 2024). "IL-1β further promotes the release of other cytokines, such as tumor necrosis factor-alpha (TNF-α) and interleukin-6 (IL-6), and the recruitment of neutrophils, perpetuating the inflammatory response and causing the severe pain and swelling characteristic of gout flares." (PMID 39409183, 2024). "In addition, IL-6 was associated with inflammatory activity in gout, the presence of tophi and articular deformities and IL-10 down-regulated the inflammatory responses in gout through inhibition of TNF-α, MIP-1α, and MIP-1β in MSU crystal–stimulated cells." (PMID 38711064, 2024). "The ability of the ceRNA network to predict miRNAs and lncRNAs upstream of CXCL8, CXCL1, CXCL2, IL-1β, and IL6 may lead to the use of a novel diagnostic and prognostic marker for gout." (PMID 38686389, 2024). "We, therefore, hypothesized that SHS stimulates an increased inflammatory cytokine IL-6 response and might be a potential risk factor for gout." (PMID 33921811, 2021). "A number of researchers have confirmed that gout shares many pathogenetic features associated with other inflammatory disorders, i.e. a rapid increase in the secretion of some pro-inflammatory cytokines (IL-1β, IL-6 and TNF-α)." (PMID 32041665, 2020). "Numerous studies have linked excessive or sustained IL-6 production with various inflammatory diseases supporting the hypothesis that IL-6 dysregulation plays a critical role in gout pathogenesis." (PMID 40170729, 2025). "Consistent with the acute gout model, the Young + Old or Young + Aged group exhibited more pronounced activation of IL-1β, IL-6, and TNF-α in peritoneal fluid and serum." (PMID 39907694, 2025). "Serum IL-6 protein expression levels were significantly elevated in patients with gouty arthritis (GA) compared to healthy individuals, with multifactor logistic regression revealing an odds ratio (OR) of 2.175 for IL-6." (PMID 40170729, 2025). "The inflammatory response in gout involves various cytokines such as IL-6, IL-1β, and TNF-α, pivotal in the amplification cascade of inflammation." (PMID 40170729, 2025). "Bai Su Zi is rich in α‐linolenic acid (ALA, > 65% in Perilla seeds), an ω‐3 polyunsaturated fatty acid that alleviates gouty arthritis by modulating lipid metabolism, inhibiting IL‐6/TNF‐α, and promoting anti‐inflammatory mediators like lipoxins." (PMID 40613560, 2025). "Sang Zhi bioactive components alleviate gouty arthritis by inhibiting NF‐κB signaling to reduce IL‐6/TNF‐α release, thereby ameliorating local inflammation and pain." (PMID 40613560, 2025). "In the acute gout mouse model, IL-6 KO mice exhibited significantly reduced footpad swelling and swelling index compared to wild-type (WT) mice." (PMID 40170729, 2025). "These markers were significantly more elevated in the AG group than in the IG group, indicating a pronounced increase in serum IL-6 and other inflammatory markers in gout patients during acute episodes." (PMID 40170729, 2025). "IL-6 expression was manipulated using IL-6 agonists and IL-6 knockout (KO) mouse technology to investigate the role and impact of the IL-6-mediated JAK2-STAT1/3 signaling pathway in gout models." (PMID 40170729, 2025). "In the 6-h acute gout cell model, expression levels of IL-1β, IL-6, JAK2, STAT1/3 mRNA, and their respective proteins—including phosphorylated JAK2 and STAT1/3—were significantly elevated in the model group compared to the blank control group." (PMID 40170729, 2025).
gout (continued). "Immunohistochemical analysis showed a substantial upregulation in the expression of pro‐inflammatory markers, including TNF‐α, IL‐6, and IL‐1β, in the paw tissues of gout mice compared to the control group." (PMID 39717013, 2025). "Neutrophils residing in joints, upon encountering MSU crystals, undergo activation, phagocytose crystals, and release inflammatory mediators including IL-1β, TNF-α, and IL-6, thereby intensifying acute inflammatory gout flares." (PMID 40612947, 2025). "Contrarily, IL-6 protein levels in peripheral blood serum were significantly higher in the AG group than in the IG group, indicating rapid increases during acute gout attacks." (PMID 40170729, 2025). "Butyrate has been documented to mitigate the onset of acute gouty arthritis by inhibiting histone deacetylase and curbing the production of IL-1β, IL-6, and IL-8 in response to MSU." (PMID 40696369, 2025). "MSU crystals were injected into the footpads of IL-6 KO and WT mice to establish an acute gouty arthritis model." (PMID 40170729, 2025). "Although IL-1β plays a crucial role in the pathogenesis of the pathogenesis of gout flares, other cytokines such as IL-6, TNF-α, and TGF-β are also involved in that." (PMID 38240927, 2024). "These therapeutic effects are attributed to bioactive compounds, including cucurbitacins, flavonoids, and alkaloids, which inhibit key pro-inflammatory mediators like TNF-α, IL-1β, and IL-6—cytokines involved in the inflammatory response during gout attacks." (PMID 39409183, 2024). "Prior investigations reported that MSU-triggered inflammation induces gout formation, whereas PA promotes anti-inflammatory activities that diminish IL-6, C-reactive protein, and TNF." (PMID 39060811, 2024). "In an acute gouty arthritis model, drugs can improve the swelling of ankle tissue in rats by inhibiting the expression of inflammatory factors such as IL-6." (PMID 39220949, 2024). "In the present study, the IL-6 levels were elevated in gout patients, and positively related to ESR, CRP, D-dimer, fibrinogen, neutrophils and monocytes." (PMID 38240927, 2024). "IL-6 is an important proinflammatory mediator as it is elevated in gout flares and is noted to be elevated in SARS-CoV-2 infection." (PMID 38686242, 2024). "Cytokine levels, including IFN-γ, TNF-α, IL-2, IL-4, IL-6, IL-10 and IL-17, were detected in early-onset gout, late-onset gout and HCs." (PMID 38240927, 2024). "This modulation aids in alleviating symptoms linked to MSU-induced gouty arthritis, such as neutrophil infiltration in knee joints, joint circumference and the production of TNF-α, IL-1β, IL-6, and IL-18." (PMID 38094893, 2023). "Patients with RA had higher plasma levels of sTNFR1, IL-1β, IL-12p70, TNF and IL-6, compared to OA and gout patients (all, P < 0.05)." (PMID 37202736, 2023). "TNF-α, IL-6, and IL-1β are involved in the activation and maintenance of inflammatory responses, which serve key roles in the development and sustenance of gouty arthritis." (PMID 36824696, 2023). "In our study, plasma cytokines including IL-1β, IL-6 and IL-10 were significantly higher in RA than OA, while TNFα was higher in gout than RA." (PMID 37202736, 2023). "The expression levels of three pro-inflammatory cytokines (i.e., IL-1β, IL-6, and TNF-α) associated with gout were further investigated in serum." (PMID 35145506, 2022). "A similar observation was previously made using an NLRP3 inhibitor in a gout model, which also suppressed IL-6 and CXCL1 in synovial tissue after MSU crystal injection." (PMID 36225929, 2022). "NLRP3 and IL-1β have been identified as risk factors for gout, and it has been clinically confirmed that high levels of NLRP3, Caspase-1, IL-1β and IL-6 have been detected in serum and synovial fluid of patients." (PMID 36313318, 2022). "IL-33 not only triggers macrophage to release IL-1β, enhancing inflammation and pain; in gouty arthritis, it but also modulates bone cancer pain by regulating IL-6 and IL-1β." (PMID 36287299, 2022).
gout (continued). "Compared with normal mice, the mRNA expression levels of IL-6 and Bcl2 were significantly increased in hyperuricemic-gout mice." (PMID 35672755, 2022). "The main pathological trait of gout is endothelial activation brought on by IL-1 and IL-6 while inducing ICAM-1 expression, which increases the influx of neutrophils into the joint fluid and the subsequent influx of monocytes." (PMID 36339594, 2022). "ELISA analysis showed that the gout group significantly up-regulated the levels of IL-1β, Caspase-1, IL-6 and TNF-α, and significantly decreased the levels of IL-10, which were induced by MSU (p < 0.05)." (PMID 36313318, 2022). "Effects of total extract of Lagotis brachystachya on serum TNF-α, IL-1β, and IL-6 of rats with chronic alcoholic liver injury and gouty arthritis (x ± s, n = 8)." (PMID 36176434, 2022). "In general, the prevalence of fever in gout is driven by specific pyrogens (IL-1, IL-6, tumor necrosis factor (TNF)-α) with the inflammasome as a pivotal activator of the inflammatory cascade." (PMID 33926105, 2021). "β-Caryophyllene decreased the productions of TNF and IL-6 in the serum of gout rats, thus relieving inflammation symptoms." (PMID 33967792, 2021). "IL-6 is also an important proinflammatory cytokine that exerts an enormous impact on gout pathogenesis." (PMID 33959014, 2021). "An extract of Tu-Teng-Cao (TTC) can inhibit the secretion of cytokines TNF-α and IL-6 in synovial fluid of rats, reduce ankle joint damage, and control uric acid and inflammation to treat gouty arthritis." (PMID 34721646, 2021). "Our results showed that the expression of IL-1β, TNF-α, and IL-6 was increased in the gouty rats, and the inhibitory effect of BV was similar to or better than that of Col, a treatment drug for acute gouty arthritis." (PMID 34564665, 2021). "In this meta-analysis, it is reported that GSZD can significantly reduce serum levels of IL-6 in gout patients, suggesting that GSZD can control the inflammatory responses in gout patients." (PMID 33205687, 2020). "The concentrations of TNF-α, IL-6, IL-1β and sIgA in colon tissue (N=7/group) were notably increased in the experimental model of gouty arthritis compared with those of the normal control mice." (PMID 32670069, 2020). "Both chronic hyperuricemia and gout involve inflammation responses and stimulate the release of interleukin-1β, interleukin-6 (IL-6), tumor necrosis factor-α (TNF- α), NF-kβ, and activate the NALP3 inflammasome complex." (PMID 32687535, 2020). "IL-1β and IL-6 were both upregulated in the inflamed ankle tissue of gout model mice but much reduced in St2-/- mice." (PMID 33204337, 2020). "IL-6 can be considered a marker of activity, aggressiveness of the disease course, and treatment effectiveness in gout patients." (PMID 33456597, 2020). "Results showed that IL6 and IL-1β were significantly increased in patients with gout-derived-PMN-MDSCs compared to the control derived-PMN-MDSCs." (PMID 33154749, 2020). "Plasma concentrations of IL-1β, IL-18, IL-6, and IL-8 are elevated in the gout patients, but little is known about the role of these cytokines in the progression of gout." (PMID 31803174, 2019). "A clinical study has shown that IL-6 levels are increased in individuals with gout, correlating with clinical manifestations of the disease." (PMID 30914954, 2019). "In the one study of 957 older Italians free of renal disease or gout, having higher uric acid was associated with increased neutrophils, CRP, IL-1ra, IL-6, IL-18 and TNFα." (PMID 28786993, 2017). "Infiltration of the synovium by neutrophils is considered to be characteristic of gouty inflammation, and the development of acute inflammation in gout requires the participation of IL-17-related cytokines (IL-1, IL-6, IL-8, and TNF-α)." (PMID 26890073, 2016).